SCYGR3 (small cysteine and glycine repeat containing 3)
Description:
In the hair cortex, hair keratin intermediate filaments are embedded in an interfilamentous matrix, consisting of hair keratin-associated proteins (KRTAP), which are essential for the formation of a rigid and resistant hair shaft through their extensive disulfide bond cross-linking with abundant cysteine residues of hair keratins. The matrix proteins include the high-sulfur and high-glycine-tyrosine keratins.
Synonyms: KRTAP28-3
Gene: Protein-coding gene on chromosome 2 (227,614,538 to 227,614,840, reverse strand). Ensembl gene ENSG00000284704.
Homologues: Paralogues in human: SCYGR7 (92% identical).